INS (insulin)
Diseases named in the same sentence as INS in open-access papers (continued):
Sharing a sentence is not in itself a finding about the gene and the disease.
diabetes (continued). "These affected enzymes are not only required for glucose processing and thereby insulin secretion, but iron accumulation is also known to induce secondary complications in diabetes." (PMID 28542222, 2017). "The resultant hyperglycaemia presents a stimulus to the beta cells, which secretes large amounts of insulin after meals, and it’s directly involved in the generation of insulin resistance and diabetes." (PMID 28542472, 2017). "In our study population, only 14 people, all males, had a diagnosis of diabetes and were undergoing insulin or oral hypoglycemic agent treatment." (PMID 29379586, 2017). "Overall 4 to 6 million people with diabetes were estimated to use insulin with an estimated cost between US$ 6.9 to US$ 11.6 billion." (PMID 29163935, 2017). "The median age was 66 years (IQR: 51–78); 58.4% had diabetes, and 77.4% of the diabetic patients were prescribed with either oral anti-diabetic agents, insulin or combination therapy." (PMID 28107491, 2017). "As a first line treatment in diabetes metformin has demonstrated improved peripheral insulin sensitivity and glucose transportation after treatment in diabetic patients." (PMID 28209916, 2017). "Diabetes mellitus is defined as a hyperglycemic condition arising due to insulin resistance or impaired insulin secretion." (PMID 28642704, 2017). "Experimentally, a threshold seems to exist in the severity of diabetes, above which only insulin or combinatorial treatment can effectively normalize blood glucose." (PMID 28323959, 2017). "Mean FEV1 was 84%predicted and 31 patients (24%) had CF-related diabetes, of whom 14 (45%) were insulin dependent." (PMID 28472055, 2017). "In addition, anti-inflammatory and antioxidant effects in these foods may have beneficial effects in alleviating inflammation and oxidative stress, and decreasing insulin resistance and secretion, which are pathogenic factors in diabetes and diabetes complications." (PMID 29141668, 2017). "Diabetes diagnoses and diabetes treatments (diet, insulin, or oral antidiabetic agents) were self-reported at the time of recruitment (1993–1997)." (PMID 27832382, 2017). "In the Multi-Ethnic Study of Atherosclerosis, trans-palmitoleic acid was related with less incident diabetes and inversely with plasma fasting insulin." (PMID 28781892, 2017). "As expected, men with hypogonadism had significantly higher levels of TyG, HOMA-IR, fasting insulin, body mass index (BMI), waist circumference, TG, total cholesterol (TC) as well as higher prevalence of hypertension and diabetes (all P for trend <0.001)." (PMID 29158535, 2017). "The new paradigm connects insulin therapy with the potential to correct frequently observed changes of iron metabolism in diabetes." (PMID 28841871, 2017). "The emergence of glucose sensors has provided patients the ability to self-monitor BG levels so as to manage insulin levels, and thus control the mortality of diabetes mellitus." (PMID 28106820, 2017). "Given the prevalence of metabolic syndrome and diabetes in young adults who were obese as children or adolescents, the exploration of conventional and pharmacological strategies to improve insulin sensitivity is imperative." (PMID 28531113, 2017). "The research results endow the implantable closed-loop insulin delivery device with promising application in diabetes therapy." (PMID 30970930, 2017). "In conclusion, the results obtained from this study indicate that combined atorvastatin and low dose insulin treatment exhibit renoprotective effects and lead to the reversal of pancreatic β-cell function in streptozotocin-induced diabetes in rats." (PMID 29051569, 2017). "On the other hand, insulin resistance of the cells occurs in diabetes mellitus type 2, is the most common type of diabetes." (PMID 28878680, 2017).
diabetes (continued). "An alternative and safe method for the treatment of diabetes is islet transplantation, which can restore insulin production by implanting functioning pancreatic islets into the liver of diabetic patients." (PMID 29403437, 2017). "A longer duration of diabetes negatively affects glycemic control, possibly because of progressive impairment of insulin secretion over time as a result of β‐cell failure." (PMID 29141693, 2017). "Diabetes mellitus, insulin, glycaemia, hypoxia and oxidative stress are important stimuli that regulate endothelin levels." (PMID 28835854, 2017). "South Asian individuals had lower insulin sensitivity than white individuals up to 20 years before they were diagnosed with diabetes." (PMID 28409212, 2017). "The main results of the present evaluation are increased prescription rates of metformin and the combination of metformin and insulin since the implementation of DMP for diabetes in Bavaria in 2004." (PMID 28529546, 2017). "Type 2 diabetes mellitus (T2DM) is the most frequent subtype of diabetes characterized by high sugar (glucose) levels in blood resulting from defects in insulin secretion and/or insulin action." (PMID 28890888, 2017). "Guinea pigs with diet-induced glucose intolerance subsequently treated with STZ demonstrated an insulin-secretory capacity consistent with insulin-independent diabetes." (PMID 28093504, 2017). "Overall, concentrations of insulin and insulin analogues in vivo (in healthy individuals and in patients with diabetes) are normally low compared to the levels required to elicit a mitogenic response." (PMID 28316059, 2017). "Mineralocorticoids (MCs) are another type of hormone known to affect diabetes development, with an excess of MCs in pathological conditions such as primary aldosteronism (PA) resulting in decreased insulin sensitivity and secretion." (PMID 28900121, 2017). "Pancreatic diabetes usually manifests as “brittle diabetes” with poor glucose control due to impaired insulin, glucagon and pancreatic polypeptide." (PMID 29212278, 2017). "People with diabetes are encouraged to help manage their own disease through diet and exercise, blood pressure and glucose monitoring and insulin administration where indicated." (PMID 28490797, 2017). "These factors includes longer diabetes duration, poor glycemic control, and higher rates of macrovascular and microvascular complications as well as insulin use among deceased diabetic patients." (PMID 29176889, 2017). "Univariate analyses revealed that age, duration of diabetes, insulin therapy, BMI, systolic BP (SBP), hemoglobin, HbA1c, TC, low-density lipoprotein (LDL), eGFR, and ACR were significant risk factors for DR at the level of P < 0.20." (PMID 28924157, 2017). "Type 2 diabetes mellitus (T2D) results from a combination of insufficient insulin secretion from the pancreatic islets and insulin resistance of target cells." (PMID 28585545, 2017). "The deterioration or loss of these cells leads to an inability to meet the increasing demands for insulin needed by the body to maintain glucose homeostasis, eventually resulting in the development of diabetes mellitus." (PMID 28829354, 2017). "Type 1 diabetes mellitus (T1DM), caused by autoimmune destruction of insulin-producing beta cells, is treated with exogenous insulin therapy." (PMID 28293906, 2017). "Of note, our study excluded patients with type I or II diabetes mellitus requiring either insulin or oral hypoglycaemics for routine management which should be borne in mind in the subsequent development of this approach." (PMID 28144789, 2017). "Diabetes mellitus (DM) is defined as a group of metabolic diseases characterized by hyperglycemia (increased blood glucose level) resulting from defects in insulin secretion, insulin action, or both." (PMID 28680863, 2017).
diabetes (continued). "Overall, these data indicate cholesterol accumulation as an underlying mechanism for glucolipotoxicity-induced defects in insulin secretion and stigmasterol treatment as a potential strategy to protect β-cell function during diabetes progression." (PMID 28842702, 2017). "Specifically, the overexpression of glutathione peroxidase 1 has undesirable effects to insulin- induced signaling pathways consequently promoting type 2 diabetes mellitus." (PMID 28373910, 2017). "The PPAR-γ agonist thiazolidinedione (TZD) can improve insulin sensitivity and has great therapeutic potential for controlling type 2 diabetes mellitus." (PMID 28708885, 2017). "Administration of either leptin or insulin to the CNS in rats with streptozotocin-induced diabetes blocks this compensatory hyperphagia almost completely." (PMID 28303116, 2017). "The activation of the FFA1 receptor, expressed in L cells and the pancreas, is useful in the control of diabetes via insulin release." (PMID 28379159, 2017). "Though sulfonylurea for treatment neonatal diabetes is supported by some researchers and clinicians, insulin treatment is still acutely required in most infants with newly diagnosed diabetes mellitus to treat or prevent ketoacidosis and dehydration." (PMID 29296240, 2017). "The ideal insulin profile for any individual with diabetes will fluctuate due to lifestyle variations and metabolic influences – for example hypoglycaemia - so the physiological importance of insulin is vital for glycaemic homeostasis." (PMID 28779138, 2017). "Study found that the course of diabetes and the level of HbA1c can extend the latency period and insulin therapy can alleviate this change." (PMID 28496408, 2017). "Our data is interesting in showing similar mortality after PCI in patients with non‐insulin treated diabetes and non‐diabetic patients but increased mortality only in diabetic patients requiring insulin treatment." (PMID 28029209, 2017). "Our results demonstrated that rosa damascena extract has useful effects on insulin resistant animals and by increasing insulin sensitivity can be considered as a potential agent in control of diabetes." (PMID 29201096, 2017). "In these studies, participants with lean diabetes were mainly males and had higher frequency of insulin use indicating rapid beta cell failure." (PMID 28827839, 2017). "Diabetes is a set of pathological disorders related to an impaired insulin production and/or action." (PMID 29286314, 2017). "If genetic variation reduces the transcription of the GCK gene, the cellular activity of GCK would likely decrease and lead to impaired glucose sensing in the liver, an impaired insulin secretion of beta-cells, and eventually diabetes." (PMID 28867816, 2017). "Various inflammatory markers are associated with progression from normoglycemia to pre-diabetes (IL13, EN-RAGE, CRP), T2D (IL13, IL17, CRP) or insulin therapy start (IL13)." (PMID 28258520, 2017). "For example, costly medications for diabetes, including insulin, would be particularly problematic in the case of poor adherence." (PMID 28228140, 2017). "Insulin treatment is generally acutely required in most infants with newly diagnosed diabetes mellitus to treat or prevent ketoacidosis and dehydration." (PMID 29296240, 2017). "As reported by others and observed by our present study, RA supplement attenuates the pathological progression of diabetes, which is evidenced by decreased water and feed intake, lowered blood glucose level, and increased insulin level." (PMID 28840833, 2017). "Odds ratio for development of diabetes over four years according to baseline insulin resistance, insulin secretion assessed by HOMA index and Lp(a) levels." (PMID 28510610, 2017). "Diabetes mellitus (DM) is a complex, chronic illness characterized by a heterogeneous set of metabolic disorders, including hyperglycemia and impaired carbohydrate, protein, and lipid metabolism, caused by abnormalities in insulin action and/or secretion." (PMID 29157252, 2017).
diabetes (continued). "Diabetes mellitus (DM) is a metabolic disorder accompanied by hyperglycemia due to inadequate insulin secretion or insulin resistance." (PMID 28448463, 2017). "STZ can cause irreversible damage to pancreatic islet β-cells, inducing insulin secretion disorders, and resulting in the occurrence of diabetes." (PMID 28970780, 2017). "Serum hepcidin levels and YKL-40 levels were measured in control group (n = 20), persons with prediabetes (n = 30) and persons with diabetes on insulin therapy (n = 30) using ELISA method." (PMID 28841871, 2017). "The first macro-level influence on diabetes educator role boundaries was the rescheduling of insulin from schedule III to IV which came into effect in December 2000." (PMID 28702089, 2017). "After a median 10 years (IQR 5–22) of diabetes 69% of patients were treated with insulin but there was significant endogenous insulin present in 24/25 patients at recruitment." (PMID 29026101, 2017). "The significant pulsatile glucose-triggered insulin release endowed the device with promising application for diabetes therapy." (PMID 30970930, 2017). "Among all participants with diabetes, 45.7% were treated with medications or insulin, while this percentage was 88.1% among participants with previously diagnosed diabetes." (PMID 28685050, 2017). "Attenuation of mTORC1in diabetes quells insulin-signalling network-wide, except for the mTOR incomplex 2 (mTORC2)-catalysed phosphorylation of protein kinase B (PKB) atSer473 (PKB-S473P), which is increased." (PMID 27986865, 2017). "The present study examined self-reported hypoglycemia in a sample of patients with insulin-treated diabetes who were being managed at a university hospital diabetes clinic and accurately represented the population base." (PMID 28913365, 2017). "The early-onset diabetes had increased first phase insulin release but similar late phase insulin release with late-onset diabetes." (PMID 28422176, 2017). "Since lipoprotein lipase (LPL) is activated by insulin, triglycerides tend to accumulate when secretion of insulin deteriorates due to diabetes." (PMID 29089472, 2017). "Physiological insulin secretion exhibits various temporal patterns, the dysregulation of which is involved in diabetes development." (PMID 29118381, 2017). "The body weight for the controls was 354 ±2 g and that for diabetes were 271±10 g and that for diabetes and insulin were 284±13g." (PMID 29121074, 2017). "Bacterial transformation is a technique of prime importance in field of genetic engineering where it finds applications from construction of genomic libraries to production of recombinant insulin for treatment of diabetes." (PMID 28819202, 2017). "Diabetes was induced by an injection of streptozotocin (60 mg/kg, IP), lycopene (4 mg/kg/day) was given to the lycopene treated groups as gavages, and insulin (Sc, 1-2 U/kg/day) was injected to the groups treated with insulin." (PMID 28656152, 2017). "In the case of the type of treatments for diabetes, the EQ-5D index of the oral hypoglycemic drugs and the insulin was lower than the other treatment groups." (PMID 28683734, 2017). "Diabetes mellitus (DM) is a well-known group of metabolic disorders characterized by hyperglycemia being resulted from abnormal insulin secretion and/or action." (PMID 28883792, 2017). "Whilst the role of insulin in the acute setting has been the subject of several studies and remains contentious, the role of insulin in the chronic management of diabetes following ACS presentation requires further exploration." (PMID 28029209, 2017). "A majority of diabetics suffer a great loss of insulin resistance; hence compounds that mimic or increase insulin sensitivity are of major importance in the treatment of diabetes mellitus." (PMID 29058615, 2017).
diabetes (continued). "The insulin resistant mice (beta-cell-specific Atg7 knockout mice) model has been shown that autophagy plays a crucial role in the development of diabetes and in preserving the structure and function of pancreatic beta cells." (PMID 28612706, 2017). "In most people with type 1 diabetes mellitus and in many people with advanced type 2 diabetes mellitus, acute severe hypoglycemia induced by insulin or sulfonylurea therapy is one of the main complications that induce brain damage." (PMID 28335557, 2017). "In diabetics, depletion of intracellular myo-inositol has been observed in insulin sensitive tissues such as liver, muscle, fat, and kidney affecting local and systemic glucose uptake and disposal dynamics." (PMID 29326659, 2017). "In conclusion, dietary anthocyanins appear to be targeting insulin sensitivity through diverse mechanisms and have potential to modulate disease states like diabetes." (PMID 29023424, 2017). "We searched curated datasets of the Gene Expression Omnibus (GEO) database and identified 13 and five expression studies of diabetes and insulin responses at various tissues, respectively." (PMID 28117714, 2017). "Insulin plays a major role in glucose metabolism and insulin-signaling defects are present in obesity and diabetes." (PMID 29242563, 2017). "Metformin is highly efficient when there is enough insulin production; however, when diabetes reaches the state of failure of β-cells and resulting in a type 1 phenotype, metformin loses its efficacy." (PMID 28167928, 2017). "Tackling aberrations in glucose-stimulated insulin release such as in diabetes with pharmacological agents, which boost the secretory capacity of β-cells, is linked to adverse side effects." (PMID 28839233, 2017). "Mice with the adipose tissue-specific ablation of GLUT4, but normal GLUT4 expression in muscle, are insulin resistant and have an increased risk of developing overt diabetes; adipose tissue-specific GLUT4 KO mice are insulin resistant also in liver and muscle." (PMID 28660193, 2017). "Diabetes mellitus is a group of metabolic diseases characterised by chronic hyperglycemia resulting from impaired insulin secretion, resistance to insulin, or both." (PMID 28717589, 2017). "The Outcome Reduction with an Initial Glargine Intervention (ORIGIN) trial 39 looked at the role of additional insulin to normalize fasting blood glucose in patients with diabetes mellitus." (PMID 28029209, 2017). "There was contradictory evidence about an association between insulin dependent GDM and diabetes post-partum screening." (PMID 28451031, 2017). "A doctor working in a primary health care unit reported that a patient with type 1 diabetes mellitus reduced their insulin use by 50% after treatment with an aqueous extract of macerated V. rufa stem bark." (PMID 28981518, 2017). "Currently, the treatment for diabetes relies on the multiple daily exogenous insulin injections to persistently regulate blood glucose levels." (PMID 28772528, 2017). "Diabetes is a metabolic disease generally related to non-/under-production of insulin in the pancreas and hyperglycemia, reflected by blood glucose concentrations higher or lower than the normal range of 80–120 mg dL−1." (PMID 28820469, 2017). "In contrast, adults with cirrhosis have increased insulin levels and can develop diabetes mellitus due to increased insulin secretion by the pancreas, decreased insulin degradation by the liver and decreased glucose uptake by tissues." (PMID 29035331, 2017). "The present review reports recent research advances of insulin-based polycrystalline compounds as potential therapeutics against diabetes." (PMID 28829407, 2017). "This type of diabetes indicates insulin resistance or reduced insulin secretion with insulin resistance." (PMID 28772877, 2017). "Diabetes is a heterogeneous group of diseases resulting in hyperglycemia due to insulin secretory dysfunction as well as insulin resistance." (PMID 28438156, 2017).